TMEM119 (transmembrane protein 119)
Description:
Plays an important role in bone formation and normal bone mineralization. Promotes the differentiation of myoblasts into osteoblasts. May induce the commitment and differentiation of myoblasts into osteoblasts through an enhancement of BMP2 production and interaction with the BMP-RUNX2 pathway. Up-regulates the expression of ATF4, a transcription factor which plays a central role in osteoblast differentiation. Essential for normal spermatogenesis and late testicular differentiation (By similarity).
Synonyms: OBIF
Tractability: Antibody: UniProt places it where antibodies can reach, with high confidence; its Gene Ontology location is reachable by antibodies, with high confidence; UniProt predicts a signal peptide or a membrane-spanning region.
Gene: Protein-coding gene on chromosome 12 (108,589,851 to 108,598,320, reverse strand). Ensembl gene ENSG00000183160.
Subcellular location: Cell membrane; Cytoplasm; Endoplasmic reticulum membrane; Secreted
Gene Ontology:
Biological process: positive regulation of bone mineralization; positive regulation of osteoblast differentiation; positive regulation of osteoblast proliferation; BMP signaling pathway; endochondral ossification; negative regulation of bone resorption; negative regulation of myotube differentiation; positive regulation of bone development; positive regulation of gene expression; spermatid differentiation; spermatogenesis; ossification
Cellular component: extracellular region; plasma membrane; cytoplasm; endoplasmic reticulum membrane; endoplasmic reticulum
Genetic constraint (gnomAD): Loss-of-function variants: 0 observed, 0.56 expected, observed/expected ratio (o/e) 0, 90% interval 0 to 1.82. That is too few expected variants to judge how well the gene tolerates losing a copy. Missense variants: 409 observed, 381.14 expected, observed/expected ratio (o/e) 1.07, 90% interval 0.99 to 1.16. Synonymous variants: 182 observed, 175.64 expected, observed/expected ratio (o/e) 1.04, 90% interval 0.92 to 1.17.
Homologues: Orthologues: chimpanzee TMEM119 (99% identical), macaque TMEM119 (94% identical), rabbit TMEM119 (76% identical), dog TMEM119 (75% identical), mouse Tmem119 (67% identical), rat Tmem119 (65% identical), tropical clawed frog tmem119 (33% identical), zebrafish tmem119b (23% identical).
Diseases named in the same sentence as TMEM119 in open-access papers:
TMEM119 is named in the same sentence as 77 diseases in open-access papers, as found by Europe PMC text mining. Sharing a sentence is not in itself a finding about the gene and the disease. The quoted sentences say what the papers report.
Alzheimer disease (23 papers, 2018 to 2026). A progressive, neurodegenerative disease characterized by loss of function and death of nerve cells in several areas of the brain leading to loss of cognitive function such as memory and language. "There is an emerging evidence that suggests that damage associated microglia (DAMs) have been shown to decrease in expression of TMEM119 in association with the development of Alzheimer’s disease." (PMID 32345303, 2020). "In a mouse model of Alzheimer’s disease (AD), TMEM119, a microglia – specific marker, is significantly reduced during amyloid plaque formation and is closely related to the spatial distribution of microglia near Aβ plaques." (PMID 41019422, 2025). "In brains affected by Alzheimer’s disease, TMEM119 was documented to be expressed on microglia with ramified and amoeboid morphologies, indicating a late infiltration by microglia due to time of development of the ischemic damage." (PMID 32833183, 2021). "Surveying the 4158 TMEM119+ cells captured from cortical tissue sections of six subjects obtained from Rush Alzheimer’s Disease Center, we find that TMEM119 + VASP + microglia are less ramified than TMEM119 + VASP− cells (P = 3 × 10-8, β = −0.26)." (PMID 33446646, 2021). "While Tmem119 is detectable in Alzheimer’s disease, its expression was significantly reduced." (PMID 38308250, 2024). "In addition, brains with known Alzheimer’s disease were shown to have higher TMEM119 mRNA levels, further supporting the role of TMEM119-positive microglia in the central response to stress, inflammation, and toxicity." (PMID 36979326, 2023). "TMEM119 is highly expressed on subclusters of microglial cells with more homeostatic properties, and this subcluster is partly lost with increasing age and in neurodegeneration as observed in Alzheimer's disease and amyotrophic lateral sclerosis brain tissue." (PMID 33410555, 2021). "Furthermore, TMEM119 expression could be detected in human post-mortem samples of Alzheimer’s disease and traumatic brain injury." (PMID 38308250, 2024). "Interestingly, PU.1, which was proposed to be a key transcription factor for regulating TMEM119 expression, also acts as an upstream regulator of TREM2, suggesting a functional role of TMEM119 in the pathological changes associated with Alzheimer’s disease." (PMID 34571885, 2021). "Dysfunctional microglia in the post-mortem Alzheimer’s disease brain are characterised by the downregulation of homeostatic markers, including P2RY12 and TMEM119, and the up-regulation of dysfunctional markers, including L-ferritin." (PMID 37118836, 2023). "Consistent with recent studies in pre-clinical models of Alzheimer’s disease (AD) and EAE, we also report both Tmem119 and P2RY12 expression are decreased after acute ischemic stroke, after the development of symptoms in CAA models, and in ex vivo models of inflammation for sorted MG." (PMID 33261619, 2020). "Tmem119 expression was shown to be elevated in the brains of patients with Alzheimer’s disease, but not in those with amyotrophic lateral sclerosis or Parkinson’s disease." (PMID 30687011, 2018). "Tmem119 has been reported to be IHC-positive in microglia but not in peripheral immune cells and was used to distinguish resident microglia from migrated peripheral cells in Alzheimer’s disease and glioma." (PMID 36204141, 2022). "Notably, TMEM119, as a distinctive marker of microglia, was expressed exclusively on a subset of Iba1+ CD68+ microglia with ramified and amoeboid morphologies in the brains of neurodegenerative diseases, such as Alzheimer's disease (AD)." (PMID 32377265, 2020).
Stroke (18 papers, 2019 to 2024). Sudden impairment of blood flow to a part of the brain due to occlusion or rupture of an artery to the brain. "The statistical analysis showed a significant increase in the relative frequency of the CD45high subpopulation as a percent of Tmem119+ cells after stroke which was associated with a significant decrease in Tmem119 and P2RY12 expressions." (PMID 33261619, 2020). "These stroke-associated white matter microglia (SAWM) showed lower expressions of the homeostatic microglial markers (P2ry12, Tmem119, etc.)along with elevated expressions of the DAM- and/or MGnD-related genes (Apoe, Trem2, Ctsb, Ctsd, etc.)." (PMID 38509618, 2024). "We report a significant increase in circulating TMEM119+/CD14+ EVs 28-days post-stroke in comparison to baseline levels and saline-injected rats, which correlated weakly with stroke volume." (PMID 36721258, 2023). "To confirm the presence of TMEM119+/CD14+ EVs in plasma we performed co-immunoprecipitation using TMEM119+ EVs isolated from 28-day post-stroke rat plasma." (PMID 36721258, 2023). "As such, we next generated mice deficient for Ripk2 in microglia using the Cre-lox system under the control of the Tmem119 promoter and subjected them to stroke." (PMID 37777791, 2023). "TMEM119+/MHC-II+ EVs were significantly increased in plasma samples 28 days post-stroke (6184 eV/μL ± 510.6) in comparison to baseline samples (3730 eV/μL ± 602 p = 0.0156) and saline injected rats." (PMID 36721258, 2023). "TMEM119+/MHC-II+ EVs were also increased post-stroke in comparison to baseline and saline-injected animals." (PMID 36721258, 2023). "Consistently, the protein level of TNF-α was also up-regulated in Tmem119-CreERT2; Nr4a1fl/fl mice at 24 h after stroke." (PMID 37486903, 2023). "Our findings suggest that sex and menopause are not factors that influence the morphological response of microglia to ischemic stroke injury or post-stroke microglia TMEM119 protein expression." (PMID 33618737, 2021). "Specifically, brain resident CD45intCD11b+Tmem119+P2RY12+ cells can alter their surface expression patterns after stroke, in symptomatic CAA, or with aging and can appear in the CD45high gate in flow cytometry studies." (PMID 33261619, 2020). "With the bilateral ICV administration, we noted a 94% reduction in TMEM119+ residential microglia 5 weeks post-injection and 3 weeks post-stroke as measured by flow cytometry." (PMID 32345303, 2020). "Future experiments that include the analyses of the brain tissue, blood, and brain lymphatic samples after a stroke at multiple time points will be of great value in clarifying potential sources of Tmem119+P2RY12+ cells following ischemia." (PMID 33261619, 2020). "At the same time, these results also suggest that lesser “macrophage-like cells” (GFP+;TMEM119− cells) were invaded into the mutant cortex after stroke." (PMID 31771656, 2019). "Indeed, infiltrating MDMs can adopt a microglial signature in animal models of multiple sclerosis and a significant proportion of CD45hi cells express bona fide microglial markers like Tmem119 and P2ry12 in models of stroke and cerebrovascular degeneration." (PMID 37248507, 2023). "TMEM119+/CD14+ EVs were weakly correlated with stroke volume suggesting that the extent of tissue damage may be reflected by circulating microglial-EVs, however this finding requires further validation with a larger sample size." (PMID 36721258, 2023). "Unsupervised analysis of the flow cytometry data with respect to the seven surface parameters of CD45, CD11b, MHC-II, CD80, P2RY12, and Tmem119 detected several subsets of MG, lymphocytes and infiltrating monocytes visualized as a phonographic comparison of the vehicle and treated GF stroke brains." (PMID 37790313, 2023). "Therefore, a time course of TMEM119 protein expression in adult stroke would be a valuable investigation as a qualitative marker of microglia during both the acute and chronic stages of ischemic stroke." (PMID 33618737, 2021).
Stroke (continued). "Similarly, in two stroke models, macrophages infiltrating the CNS or ectopically placed in peri-infarct areas, became TMEM119+ and/or P2RY12+ and/or Sall1+." (PMID 34311763, 2021). "It is plausible that the detectability of TMEM119 may also vary at different time points after stroke." (PMID 33618737, 2021). "All CD45intCD11b+ cells in both sham and stroke were Tmem119+P2RY12+." (PMID 33261619, 2020). "However, such a reduction in GFP+;TMEM119+ cell density in response to the stroke was diminished in the mutant peri­infarct area as compared with that of controls." (PMID 31771656, 2019). "In the plasma assays of both TMEM119+/CD14+ and TMEM119+/ MHC-II+ EVs, dual-labelled EVs were increased at 28 days post-stroke, but insignificantly at 7-days post-stroke." (PMID 36721258, 2023). "We demonstrate that Tmem119 and P2RY12 expression is evident within both CD45int and CD45high myeloid populations in models of stroke, CAA, and aging." (PMID 33261619, 2020). "In the ischemic penumbra, outside of the stroke core, microglia had reduced process ramification, reduced P2RY12 and TMEM119 protein expression, and less frequent or reduced CXCL10 expression." (PMID 32573436, 2020). "Microglia-like cells were present 62 days post-stroke, with many exhibiting a ramified morphology, P2RY12 and TMEM119 immunopositivity and expression of Sall1 mRNA." (PMID 33363542, 2020). "NPD1 and RvD1 increased both Fcrls and Tmem119, increasing the quantity of homeostatic and non-reactive microglia following stroke onset." (PMID 37270727, 2023). "Immunofluorescence histochemistry confirmed co-expression of CD14 and TMEM119 within the stroke-induced striatum, with no detectable expression of CD14 within the contralateral striatum." (PMID 36721258, 2023). "Therefore, circulating levels of TMEM119+/MHC-II+ EVs were also evaluated at baseline, 7- and 28-days post-stroke." (PMID 36721258, 2023). "TMEM119+/ MHC-II+ EVs were significantly increased at 28-days in the control saline injections (likely due to mechanical injury) and even more so in the ET-1 injected stroke rats." (PMID 36721258, 2023). "The temporal expression pattern of TMEM119 post-stroke has not been well characterized and further work is necessary to determine its reliability in the acute phase of neurological injury." (PMID 36721258, 2023). "MHC-II surface expression of CD45highCD11b+Tmem119+P2RY12+ subpopulation was significantly higher than CD45intCD11b+Tmem119+P2RY12+, suggesting a higher activation state of these CD45high cells after stroke." (PMID 33261619, 2020). "We also reported that no significant population of Tmem119+P2RY12+ cells are present in the peripheral blood of sham or MCAO mice 3 days after stroke." (PMID 33261619, 2020). "Data showed that regardless of a stroke status, post-Percoll brain Tmem119+ cells acutely upregulate expression of CD45 in response to an inflammatory LPS stimulus." (PMID 33261619, 2020). "Moreover, PLX5622 treatment significantly reduced Tmem119 expression in brains after stroke, compared to naïve or normal diet administered brains (p < 0.05, compared to naïve and ND-stroke)." (PMID 36824976, 2023). "Importantly, a small subpopulation of resident MG that express both Tmem119 and P2RY12 may fall within the CD45highCD11b+ gate that is functionally distinct after stroke when compared to the large subpopulation of resident MG identified as CD45intCD11b+." (PMID 33261619, 2020). "Interestingly, a significant subpopulation of CD45highCD11b+ population was Tmem119+P2RY12+ in stroke but not in sham brains." (PMID 33261619, 2020). "In this study, we used Tmem119 and P2RY12 along with a conventional combination of CD45, CD11b, and Ly6C myeloid markers in models of stroke, CAA, and aging to determine whether Tmem119+P2RY12+ cells appear within the CD45highCD11b+ gate, often referred to as the “infiltrating myeloid” gate." (PMID 33261619, 2020).
Stroke (continued). "Using nanoflow cytometry, TMEM119+/CD14+ EVs were directly labelled in the plasma and demonstrate an increase 28-days post-stroke, but not 7-days post-stroke." (PMID 36721258, 2023).
glioma (14 papers, 2019 to 2024). A benign or malignant brain and spinal cord tumor that arises from glial cells (astrocytes, oligodendrocytes, ependymal cells). "Herein, we show that Tmem119 is highly expressed by MG (both in control and glioma conditions), and Lgals3 (encoding Gal-3) by infiltrating Mo/MΦ at RNA and protein levels." (PMID 33608526, 2021). "(a) The log-fold change expression of SGmic genes (P2ry13, P2ry12, Gpr34, Slc2a5, Siglec-H, Olfml3, Tmem119, Fcrls) in glioma-associated microglia isolated from experimental RCAS tumors compared to microglia isolated from healthy control brains is shown." (PMID 30764877, 2019). "(c) Graph shows the log-fold change expression of SGmic genes (P2ry13, P2ry12, Gpr34, Slc2a5, Siglec-H, Olfml3, Tmem119, Fcrls) in glioma-associated microglia isolated from GL261 tumors as compared to microglia isolated from healthy control brains." (PMID 30764877, 2019). "(b) The log-fold change expression of SGmic genes (P2ry13, P2ry12, Gpr34, Slc2a5, Siglec-H, Olfml3, Tmem119, Fcrls) in glioma-associated microglia isolated from RCAS tumors compared to microglia isolated from healthy control brains is shown." (PMID 30764877, 2019). "For instance, the disease-associated microglia (GAMs in glioma, ischemic-associated MG in MCAO, and DAM and IRM in SAH exhibit a decrease in several microglial core genes such as CX3CR1 and TMEM119, a high presence of inflammatory signatures, and an upregulation of distinct proliferation markers." (PMID 38665919, 2024). "Subsequently, we further evaluated the representative glioma‐associated microglia/macrophage (GAM)‐related genes expression level between high‐ and low‐risk group, higher expression level of IBA1, TMEM119, CD68, CSF1R, and TGFB1 was found in the high‐risk group." (PMID 35985661, 2022). "Staining for Tmem119 and Gal-3 separates MG and Mo/MΦ in murine gliomas." (PMID 33608526, 2021). "The pattern of TAM development in glioma started first with a microglia phenotype (P2RY12+/TMEM119+), then it turned to polarized macrophage (CD163+), and finally converged into M2b macrophages (IL1RN+) with activated expression of strong angiogenesis signaling molecules (VEGFA)." (PMID 34692159, 2020). "Our in vitro glioma IHC analysis also confirmed the riskscore positively correlated with IBA1, TMEM119, CD68, CSF1R, and TGFB1 protein expression." (PMID 35985661, 2022). "We have demonstrated that microglia can be delineated from TAMs in immunohistochemically stained human glioma tissue using the immunoreactivity of microglial-specific markers P2RY12 and TMEM119." (PMID 34286275, 2021). "Polychromatic immunofluorescence revealed that SIRPB1 co-localizes with TMEM119 (microglia marker), CD86 (M1 macrophage marker), and CD163 (M2 macrophage marker) indicating that SIRPB1 is predominantly found in TAMs, which in glioma tissues exhibit both M1 and M2 characteristics." (PMID 38594692, 2024). "Different from Iba1+ macrophage, TMEM119+ microglia was not accumulated during tumor progression, indicating that Siglec-15 was predominantly expressed in peripheral monocyte-derived macrophages of glioma TME." (PMID 37234161, 2023). "This fully confirmed MDM as CD49d-positive and TMEM119-negative cells and corroborated that 25% of all TAM (at seven days of glioma-expansion) are contributed by microglial cells." (PMID 34298846, 2021).